RANGAP1 (Ran GTPase activating protein 1)
Description:
GTPase activator for RAN. Converts cytoplasmic GTP-bound RAN to GDP-bound RAN, which is essential for RAN-mediated nuclear import and export. Mediates dissociation of cargo from nuclear export complexes containing XPO1, RAN and RANBP2 after nuclear export.
Synonyms: KIAA1835; SD; Fug1; RANGAP
Tractability: Small molecule: a structure with a bound ligand is known. PROTAC: UniProt records ubiquitination sites on it; ubiquitination databases record sites on it; its protein half-life has been measured.
Gene: Protein-coding gene on chromosome 22 (41,244,779 to 41,286,272, reverse strand). Ensembl gene ENSG00000100401.
Subcellular location: Cytoplasm; Nucleus, nucleoplasm; Nucleus envelope; Chromosome, centromere, kinetochore; Cytoplasm, cytoskeleton, spindle
Subcellular location (Human Protein Atlas): Nuclear membrane; Cytosol; Flagellar centriole; Vesicles
Pathways (Reactome):
Cell Cycle: Amplification of signal from unattached kinetochores via a MAD2 inhibitory signal; EML4 and NUDC in mitotic spindle formation; Mitotic Prometaphase; Postmitotic nuclear pore complex (NPC) reformation; Resolution of Sister Chromatid Cohesion; Separation of Sister Chromatids
Metabolism of proteins: SUMOylation of DNA replication proteins; SUMOylation of nuclear envelope proteins
Disease: Rev-mediated nuclear export of HIV RNA
Signal Transduction: RHO GTPases Activate Formins
Gene Ontology:
Molecular function: cadherin binding; GTPase activator activity; protein binding; RNA binding; small GTPase binding
Biological process: activation of GTPase activity; negative regulation of protein export from nucleus; nuclear export; protein sumoylation; signal transduction
Cellular component: cytoplasm; cytosol; kinetochore; nuclear envelope; nuclear membrane; perinuclear region of cytoplasm; SUMO ligase complex; nuclear pore; nucleus; nucleoplasm; spindle
Genetic constraint (gnomAD): Loss-of-function variants: 38 observed, 61.61 expected, observed/expected ratio (o/e) 0.62, 90% interval 0.47 to 0.81. The upper end of that interval is the gene's LOEUF score, 0.81, which puts it in group 3 of 6, group 1 being the genes least tolerant of losing a copy. Missense variants: 630 observed, 739.21 expected, observed/expected ratio (o/e) 0.85, 90% interval 0.8 to 0.91. Synonymous variants: 329 observed, 311.26 expected, observed/expected ratio (o/e) 1.06, 90% interval 0.96 to 1.16.
Homologues: Orthologues: chimpanzee RANGAP1 (94% identical), pig RANGAP1 (92% identical), dog RANGAP1 (92% identical), rabbit RANGAP1 (91% identical), guinea pig RANGAP1 (90% identical), rat Rangap1 (90% identical), macaque RANGAP1 (88% identical), mouse Rangap1 (88% identical), tropical clawed frog rangap1 (69% identical), zebrafish rangap1a (59% identical), zebrafish rangap1b (56% identical), Drosophila melanogaster RanGAP (35% identical), and 1 more.
Diseases named in the same sentence as RANGAP1 in open-access papers:
RANGAP1 is named in the same sentence as 50 diseases in open-access papers, as found by Europe PMC text mining. Sharing a sentence is not in itself a finding about the gene and the disease. The quoted sentences say what the papers report.
gastric cancer (15 papers, 2016 to 2023). A primary or metastatic malignant neoplasm involving the stomach. "High expression of circ-RanGAP1 has a significant association with lymph node metastasis, advanced TNM stage, and worse survival in patients with gastric cancer and contributes to gastric cancer progression dependent on the miR-877-3p/VEGFA pathway." (PMID 35813866, 2022). "circ-RanGAP1 is elevated in plasma exosomes from gastric cancer patients and facilitates gastric cancer invasiveness by upregulating VEGFA expression." (PMID 34109113, 2021). "Specially, circRNA_0079586 was found to accelerate the progression of glioma via interacting with miR-183-5p, while circRNA_RanGAP1 was found to facilitate gastric cancer invasion and metastasis via interacting with miR-877-3p29,30." (PMID 34611229, 2021). "Circ-RanGAP1 was significantly up-regulated in both human and gastric cancer tissues, and its high expression level was closely related to TNM staging, lymph node metastasis, and poor survival." (PMID 33613113, 2021). "This suggests that circ-RanGAP1 has the potential to be a marker for preoperative diagnosis and prognostic monitoring of gastric cancer." (PMID 33613113, 2021). "For example, circ‐SHKBP1 and circ‐RanGAP1 in gastric cancer (GC) are reported to be up‐regulated and effectively delivered from GC‐derived EVs into the circulation." (PMID 33586248, 2021). "Lu et al35 studied the up‐regulation of circ‐RanGAP1 in gastric cancer (GC)." (PMID 33277969, 2022). "In individuals with gastric cancer, plasma exosomal circ‐RanGAP1 levels are relevant to lymph node metastasis and poor clinical outcome, and a prognostic model integrating circ‐RanGAP1 and TNM stage showed an effective prognostic value (AUC, 0.830) compared with individual models." (PMID 34898043, 2021). "Circ-RanGAP1 in gastric cancer, circUHRF1 in hepatocellular carcinoma, and circFMN2 in colorectal cancer may be useful as tumor markers, as well as diagnostic and treatment targets." (PMID 34249673, 2021). "The results showed that circ-RanGAP1 in gastric cancer, circUHRF1 in hepatocellular carcinoma, and circFMN2 in colorectal cancer regulate the malignant behavior of tumors and affect the expression of their host gene through sponging miR-877-3p, miR-449c-5p, and miR-1182, respectively." (PMID 34249673, 2021). "Interestingly, we found that circ-RanGAP1 and its host gene in gastric cancer, circUHRF1, as well as its host gene in hepatocellular carcinoma exhibited the same expression pattern." (PMID 34249673, 2021). "Both circ-RanGAP1 and its host gene were highly expressed in gastric cancer." (PMID 34249673, 2021). "Similarly, Gastric cancer (GC)-derived exosomal short hairpin kinesin-binding protein circRNA (circshKBP) and Ran guanosine triphosphatase-activating protein 1 circRNA (circ-RanGAP1) have also been reported to act as specific miRNA sponges to promote neovascularization." (PMID 37753074, 2023). "Circ-RanGAP1 sponges miR-877-3p to raise VEGFA production and boosts gastric cancer invasion and metastasis." (PMID 35821230, 2022). "Among them, RAB3A interacting protein (RAB3IP), Ran GTPase-activating protein 1 (RanGAP1), and KIAA1244 exhibited a fold change >2, indicating significantly high expression in gastric cancer." (PMID 34249673, 2021). "RAB3IP, RanGAP1, and KIAA1244 are host genes of exosomal circRNA which exhibited more than two-fold differences in gastric cancer." (PMID 34249673, 2021). "At the same time, circ-RanGAP1/miR-877-3p may have 10 binding sites, such as DNMT1 in gastric cancer." (PMID 34249673, 2021).
colorectal cancer (4 papers, 2021 to 2025). A primary or metastatic malignant neoplasm that affects the colon or rectum. "The expression of METTL3 was not only significantly upregulated in colorectal cancer and associated with a poor prognosis in patients but also showed the positive correlation with RanGAP1 across TCGA, KMplot, GSE39582 and GSE161158 datasets." (PMID 38267624, 2024). "Ran GTPase activating protein 1 (RanGAP1) has been implicated in various diseases, but its role in colorectal cancer (CRC) progression remains unclear." (PMID 38267624, 2024). "METTL3 mediates Ran GTPase activating protein 1 (RanGAP1) to contribute to the progress of colorectal cancer (CRC)." (PMID 41256854, 2025). "Previous studies have demonstrated that RanGAP1 also exerts its regulatory effects on colorectal cancer progression via the WNT signaling pathway." (PMID 38267624, 2024). "Through RNA-seq and Western blot analysis, we have identified that RanGAP1 facilitates the progression of colorectal cancer by enhancing the phosphorylation levels within the MAPK signaling pathway." (PMID 38267624, 2024). "In conclusion, RanGAP1 may exert an influence on the progression of colorectal cancer through its regulation of the MAPK signaling pathway via CRABP2." (PMID 38267624, 2024).
breast carcinoma (3 papers, 2017 to 2022). "The effects of RanGap1 on ROS and mitochondrial function imply that RanGap1 might become a novel target in the preventive and treatment on tumors and diseases, especially in breast cancer and mitochondrial diseases." (PMID 36552538, 2022).
hepatocellular carcinoma (3 papers, 2021 to 2024). A malignant tumor that arises from hepatocytes. "The role of RanGAP1 in hepatocellular carcinoma is demonstrated by its ability to promote cell migration and invasion through the up-regulation of KMD2A expression or LASP1 SUMOylation." (PMID 38267624, 2024).
lymphoma (3 papers, 2013 to 2025). A malignant (clonal) proliferation of B- lymphocytes or T- lymphocytes which involves the lymph nodes, bone marrow and/or extranodal sites. "Given that ON 01910.Na is currently under a randomized phase III trial for patients with refractory myelodysplastic syndrome, this drug would be very promising for the RanGAP1-targeted lymphoma therapy." (PMID 24223200, 2013). "Moreover, RanGAP1 knockdown induced lymphoma cell death and cell-cycle arrest." (PMID 27228340, 2016). "Therefore, RanGAP1 is an appropriate lymphoma marker with the potential for tumor-targeted therapy." (PMID 24223200, 2013).
B-cell lymphoma (2 papers, 2013 to 2015). "Further, RanGAP1 has been found as a potential marker and therapeutic target for aggressive B-cell lymphoma, especially diffuse large B-cell lymphoma (DLBCL)." (PMID 26506250, 2015). "RanGAP1 was also highly expressed in other B-cell lymphomas (BCL, n = 180) with brisk mitotic activity (B-lymphoblastic lymphoma/leukemia: 93%, and Burkitt lymphoma: 95%) or cell-cycle dysregulation (mantle cell lymphoma: 83%, and Hodgkin’s lymphoma 91%)." (PMID 24223200, 2013). "Therefore, RanGAP1 is a promising marker and therapeutic target for aggressive B-cell lymphoma, especially DLBCL." (PMID 24223200, 2013).
intracranial aneurysm (2 papers, 2021 to 2024). "In patients with ruptured intracranial aneurysms, the expression of MPO was up-regulated with promoted expression of circRNA_0079586 and circRNA_RanGAP1." (PMID 34611229, 2021).
lymph node metastases (2 papers, 2022 to 2025). "The higher expression of exosomal circ-RanGAP1 in GC was significantly related to lymph node metastasis, TNM stage, and poor survival." (PMID 35755416, 2022).
melanoma (2 papers, 2015). A malignant, usually aggressive tumor composed of atypical, neoplastic melanocytes. "Consistent with this, four key nuclear transport factors, including CRM1, RanGAP1, Ran and RanBP1, are overexpressed in metastatic melanomas compared to primary melanomas and melanocytic nevi." (PMID 26506250, 2015).
schizophrenia (2 papers, 2016 to 2022). A major psychotic disorder characterized by abnormalities in the perception or expression of reality. "We found that RGS4 and RANGAP1 both had multiple significant meta path types indicating their potential associations and mechanisms associated with schizophrenia." (PMID 35412455, 2022).
brain glioma (1 paper, 2024). A malignant glioma that involves the brain. "Subsequent in vitro experiments explored the interaction between RANGAP1 and the Smad signaling pathway in brain glioma cells." (PMID 38801243, 2024). "Furthermore, we assessed the impact of RANGAP1 and SUMO1 treatments on the growth of brain glioma cells and the Smad signaling pathway." (PMID 38801243, 2024).
Burkitt lymphoma (1 paper, 2013). A rare form of malignant mature B-cell non-Hodgkin lymphoma. "Interestingly, RanGAP1 was frequently expressed in tumors with brisk mitotic activity (B-lymphoblastic lymphoma/leukemia: 93.3%, and Burkitt lymphoma: 94.6%) or with cell-cycle aberrations (mantle cell lymphoma: 83.3%, and Hodgkin’s lymphoma: 90.5%)." (PMID 24223200, 2013). "As a cell-cycle regulator, RanGAP1 was also frequently overexpressed in other BCL with brisk mitotic activity (lymphoblastic lymphoma/leukemia, and Burkitt lymphoma) or cell-cycle deregulation (mantle cell lymphoma and Hodgkin’s lymphoma), but only occasionally in low-grade BCL." (PMID 24223200, 2013).
colon adenocarcinoma (1 paper, 2024). "To assess the expression level of RanGAP1 in cancer, we utilized The Cancer Genome Atlas (TCGA) database and observed elevated levels of RanGAP1 in several cancers, including Colon Adenocarcinoma (COAD) and Rectum Adenocarcinoma (READ)." (PMID 38267624, 2024).
endometriosis (1 paper, 2021). The growth of functional endometrial tissue in anatomic sites outside the uterine body. "We found that the expression level of hsa_circ_0063526 (circ-RanGAP1) was higher in the endometriosis group, and bioinformatics analysis revealed that circ-RanGAP1 and miRNA-141-5p have complementary binding sites." (PMID 34967761, 2021).
follicular lymphoma (1 paper, 2013). Follicular lymphoma is a form of non-Hodgkin lymphoma characterized by a proliferation of B cells whose nodular structure of follicular architecture is preserved. "Other types of BCL showed rare or uncommon expression of RanGAP1, including small lymphocytic lymphoma (6.3%), follicular lymphoma (23.5%), marginal zone lymphoma, MALT type (16.7%), and lymphoplasmacytic lymphoma (36.4%)." (PMID 24223200, 2013).
glioma (1 paper, 2024). A benign or malignant brain and spinal cord tumor that arises from glial cells (astrocytes, oligodendrocytes, ependymal cells). "The K524R mutation in RANGAP1 further highlighted its crucial function in cell proliferation and migration, providing insights into glioma biology and opening up new options for targeted therapies." (PMID 38801243, 2024). "Examining its implications in glioma, RANGAP1 emerges as a pivotal hub gene with potential prognostic significance and dynamic expression patterns." (PMID 38801243, 2024). "Confocal microscopy images further revealed partial colocalization of SUMO1 and RANGAP1, mainly within the nuclei of glioma cells." (PMID 38801243, 2024). "Experimental studies confirmed the downregulation of RANGAP1 in glioma cells and verified that RANGAP1 repair impedes tumor growth." (PMID 38801243, 2024). "Collectively, understanding the multifaceted involvement of RANGAP1 in glioma pathogenesis offers valuable insights for targeted interventions and enhances our comprehension of glioma progression and treatment strategies." (PMID 38801243, 2024). "Since there are few studies on RANGAP1 in glioma cell experiments, we selected RANGAP1 as a hub gene for subsequent analysis." (PMID 38801243, 2024). "Our analysis results showed that BRCA1 and HDAC1 were highly expressed in gliomas, while the expression results of RANGAP1 were opposite." (PMID 38801243, 2024). "The functional role of RANGAP1 in cell cycle distribution and apoptosis was investigated by downregulating RANGAP1 in glioma cells and analyzing the effects using flow cytometry." (PMID 38801243, 2024). "qRT-PCR revealed a significant downregulation of RANGAP1 in glioma cells, which was further corroborated by WB analysis indicating lower protein levels." (PMID 38801243, 2024). "The discovery of key prognostic genes, particularly BRCA1, HDAC1, and RANGAP1, highlights their significant impact on glioma survival." (PMID 38801243, 2024). "Through bioinformatics, RANGAP1 was identified as a crucial prognostic gene for glioma." (PMID 38801243, 2024). "Our findings suggest that RANGAP1 may be a potential prognostic marker in gliomas and could play a role in regulating cell proliferation, migration, and invasion." (PMID 38801243, 2024). "Notably, RANGAP1 emerged as a key regulator affecting crucial cellular processes in glioma cells, shedding light on its potential therapeutic relevance." (PMID 38801243, 2024). "Furthermore, the knockdown of RANGAP1 disrupted cell cycle distribution and inhibited apoptosis in glioma cells." (PMID 38801243, 2024). "The significance of RANGAP1 in glioma is underscored by its multifaceted roles." (PMID 38801243, 2024). "The Cancer Genome Atlas (TCGA) Glioma and GSE16011 datasets were analyzed through bioinformatics to identify Ran GTPase activating protein 1 (RANGAP1) as the hub gene for further study." (PMID 38801243, 2024).
Hodgkins lymphoma (1 paper, 2013). A heterogeneous group of malignant lymphoid neoplasms of B-cell origin characterized histologically by the presence of Hodgkin and Reed-Sternberg (HRS) cells in the vast majority of cases. "The selective overexpression of RanGAP1 in aggressive B-cell and Hodgkin’s lymphomas may shed light on innovative targeted therapy." (PMID 24223200, 2013). "Therefore, RanGAP1 is not merely a marker of cell division, because it is also highly expressed in mantle cell and Hodgkin’s lymphomas, both of which have relatively lower proliferation activity." (PMID 24223200, 2013).
Huntington disease (1 paper, 2025). Huntington disease (HD) is a rare neurodegenerative disorder of the central nervous system characterized by unwanted choreatic movements, behavioral and psychiatric disturbances and dementia. "In Huntington’s disease (HD), mutant huntingtin disrupts the nuclear envelope and sequesters critical nuclear transport factors such as RanGAP1 and GLE1 in the nucleus which impairs RNA export." (PMID 40132021, 2025).
keloid (1 paper, 2023). An irregularly shaped, elevated mark on the skin caused by deposits of excessive amounts of collagen during wound healing. "Confocal microscopy images further demonstrated that SUMO1 partially colocalized with RanGAP1 in human keloid fibroblasts (HKFs), predominantly at the cytoplasmic fibres of NPCs." (PMID 36916534, 2023). "The immunofluorescence co‐staining results revealed that SUMOs and RanGAP1 had an obvious relationship in keloids." (PMID 36916534, 2023). "RanGAP1 was highly expressed in both samples, while the expression of SUMOs in keloid was higher than that in normal skin tissues." (PMID 36916534, 2023). "Normal skin and keloid tissues were stain with RanGAP1 and SUMOs." (PMID 36916534, 2023). "Therefore, we selected RanGAP1 as a binding partner of SUMOs to explore the regulatory mechanism of sumoylation in keloids." (PMID 36916534, 2023). "RanGAP1 acted as a synergistic, functional partner of SUMOs in keloids." (PMID 36916534, 2023). "Altogether, our results indicate that RanGAP1 acts as a functional partner of SUMOs in keloids, and the positive regulation of sumoylation in keloids might be related to RanGAP1." (PMID 36916534, 2023). "Our previous studies showed that sumoylation is positively regulated in keloids, but the regulatory role of RanGAP1*SUMO1 in keloids is still unknown." (PMID 36916534, 2023). "Thus, we speculate that the regulation of sumoylation in keloids may be related to the role of RanGAP1 in nucleocytoplasmic transport of proteins in HKFs." (PMID 36916534, 2023). "We chose to investigate RanGAP1, as a chaperone of SUMO proteins, in our study of the effect of sumoylation on keloids." (PMID 36916534, 2023). "Moreover, RanGAP1 is highly expressed in skin, but its expression in keloids has not yet been reported." (PMID 36916534, 2023). "As an intermediate carrier of sumoylation, RanGAP1*SUMO1 is hypothesized to mediate the nucleocytoplasmic transport of proteins in related signalling pathways and regulate the spatial distribution of intracellular proteins, affecting the downstream phenotype of keloids." (PMID 36916534, 2023).
prostate carcinoma (1 paper, 2016). A carcinoma that arises from epithelial cells of the prostate gland. "This DHS is located within the gene body of RANGAP1, which has previously been associated with signalling cascades in prostate cancer." (PMID 27717381, 2016).
prostate tumors (1 paper, 2011). "Findings revealed an association of SNPs surrounding ABCD3 gene with basal gene expression of RanGAP1 is important in prostate tumors in AA." (PMID 21992608, 2011).